APOC3 (apolipoprotein C3)
Diseases named in the same sentence as APOC3 in open-access papers (continued):
Sharing a sentence is not in itself a finding about the gene and the disease.
Crohn disease (1 paper, 2018). A gastrointestinal disorder characterized by chronic inflammation involving all layers of the intestinal wall, noncaseating granulomas affecting the intestinal wall and regional lymph nodes, and transmural fibrosis. "For instance, PTVs in CARD9, RNF186 and IL23R provide protection against Crohn’s disease and/or ulcerative colitis and PTVs in ANGPTL4, PCSK9, LPA, and APOC3 protect against coronary heart disease." (PMID 29691392, 2018).
Hernia (1 paper, 2018). "Apolipoproteins were analyzed with an immunoassay for multiplexed detection of APOA1, APOA2, APOB, APOC2, APOC3, and APOE, and all six proteins were found to be significantly elevated in urine samples of BC patients when compared to controls (hernia patient volunteers)." (PMID 30544619, 2018).
Hydrocephalus (1 paper, 2026). Hydrocephalus is an active distension of the ventricular system of the brain resulting from inadequate passage of CSF from its point of production within the cerebral ventricles to its point of absorption into the systemic circulation. "At an optimal cutoff value of 4,463 ng/mL, patients with high ApoC3 levels exhibited significantly worse 3-month functional outcomes and a higher incidence of delayed cerebral ischemia and hydrocephalus." (PMID 42077987, 2026). "Monitoring ApoC3 levels in CSF may be beneficial for predicting complications such as delayed cerebral ischemia and hydrocephalus in patients with aSAH." (PMID 42077987, 2026).
hyperalphalipoproteinemia 2 (1 paper, 2025). "Hyperalphalipoproteinemia 2, also known as APOC3 deficiency, is characterized by moderate-to-very high HDL-C and low triglyceride levels." (PMID 40004987, 2025). "APOC3: Genetic loss-of-function APOC3 variants are known to cause hyperalphalipoproteinemia 2 in an autosomal co-dominant manner." (PMID 40004987, 2025).
hypothyroidism (1 paper, 2022). Abnormally low levels of thyroid hormone. "Taken together, the net effect of ApoC3 in modulating serum lipid metabolism in patients with hypothyroidism is more inclined to inhibiting the biological activity of LPL and affecting the serum TG metabolism." (PMID 34784265, 2022). "It is also worth noting that the serum concentrations of ApoC3 were found to be significantly decreased in hypothyroidism mice with or without pregnancy." (PMID 34784265, 2022).
idiopathic pulmonary fibrosis (1 paper, 2025). Idiopathic pulmonary fibrosis (IPF) is a nonneoplastic pulmonary disease that is characterized by the formation of scar tissue within the lungs in the absence of any known cause. "There was suggestive evidence for an association between genetically predicted APOC3 inhibition and idiopathic pulmonary fibrosis (OR = 1.56, 95% CI=1.17 to 2.08, P=2.5e-03), although not passing the multiple testing threshold." (PMID 40052268, 2025).
Infertility (1 paper, 2023). "Although we have not been clear for the diagnosis and potential tailored management of infertility by ApoC3, it would be worthwhile to explore the application of ApoC3 as a biomarker in evaluation of infertility in women with PCOS." (PMID 37689737, 2023).
ischemia (1 paper, 2025). A hypoperfusion of the BLOOD through an organ or tissue caused by a PATHOLOGIC CONSTRICTION or obstruction of its BLOOD VESSELS, or an absence of BLOOD CIRCULATION. "To understand the role of ApoC3 in ischaemia‐driven angiogenesis, we used the hind limb ischaemia model, whereby the left femoral vascular bed is ligated and excised, and the return of blood flow to the ischaemic limb is measured regularly over 14 days." (PMID 40981413, 2025). "Despite demonstrating similarly lower triglyceride levels compared to Apoc3+/+ mice in the hindlimb ischemia model, Apoc3 deficiency did not affect ischemia‐driven angiogenesis, blood flow, or angiogenic marker expression in the hindlimb ischemia model of PAD." (PMID 40981413, 2025).
kidney stone (1 paper, 2022). "The concentration of ApoC-III in urinary excretion is significantly associated with urinary calcium excretion in children, thus suggesting that abnormalities in lipid metabolism and APOC3 might play a role in kidney stone formation." (PMID 35629966, 2022).
liver fibrosis (1 paper, 2020). "However, different alleles at APOC3 rs2070667 showed insignificant effect on ballooning (G/G vs. G/A+A/A: 2.00 (1.00 and 2.00) vs. 1.50 (1.00 and 2.00), P = 0.744) and liver fibrosis (G/G vs. G/A+A/A: 2.00 (1.00 and 3.00) vs. 1.00 (0.00 and 3.00), P = 0.201)." (PMID 33294458, 2020). "To shed light on the interaction between serum lipidomics and NAFLD, we further investigated the association of APOC3 rs2070667-related differential serum lipids and NAFLD-specific pathological disorders (hepatocyte steatosis, lobular inflammation, ballooning, and liver fibrosis)." (PMID 33294458, 2020).
macular edema (1 paper, 2021). "Increased APOC3 levels have been observed in patients with branch retinal vein occlusion with macular edema." (PMID 34602085, 2021).
osteonecrosis (1 paper, 2025). A none disease characterized by death of bone tissue due to a lack of blood supply.
Peripheral Artery Disease (1 paper, 2025). "ApoC3 deficiency (Apoc3−/−) reduced inflammatory angiogenesis, suggesting a selective role for ApoC3 in inflammation‐driven neovascularisation relevant to peripheral artery disease pathophysiology." (PMID 40981413, 2025).
pneumonia (1 paper, 2019). An acute, acute and chronic, or chronic inflammation focally or diffusely affecting the lung parenchyma, caused by an infection in one or both of the lungs (by bacteria, viruses, fungi, or mycoplasma.). "In addition, ApoA1/A2/A4 and ApoC3 up-regulated by I.T. LPS were also identified in BALF from pneumonia-associated ARDS patients in a separate study." (PMID 31373289, 2019).
Salmonella Infections (1 paper, 2026). Infections with bacteria of the genus SALMONELLA. "Recombinant typhoid toxin or Salmonella infection recapitulated LYZ and APOC3 secretion in cultured cells, which involved ATM/ATR-dependent DDRs and confirmed observations in typhoid fever." (PMID 41326716, 2026).
transmissible spongiform encephalopathies (1 paper, 2011). "Several studies have also reported the involvement of many members of the apolipoprotein gene family (ApoA1, ApoA4, ApoC1, ApoC2, ApoC3 and ApoD) in transmissible spongiform encephalopathies." (PMID 21629698, 2011).
typhoid fever (1 paper, 2026). A bacterial infectious disorder contracted by consumption of food or drink contaminated with Salmonella typhi. "In summary, we find that toxin-induced DDRs modulates expression and secretion of APOC3, which was identified in human participants with acute typhoid fever." (PMID 41326716, 2026). "The findings indicate that increased APOC3 originated from infected intestinal epithelial cells rather than liver cells during typhoid fever." (PMID 41326716, 2026).
cardiovascular disease (92 papers, 2010 to 2026). "It has been reported that individuals with elevated plasma levels of ApoC3 have an elevated risk of experiencing cardiovascular diseases." (PMID 39798876, 2025). "Apolipoprotein C3 (apoC3) is a key regulator of triglyceride metabolism and has emerged as a potential therapeutic target for reducing the risk of cardiovascular disease." (PMID 41002378, 2025). "Dysfunctional HDL and elevated levels of APOC3 have been associated with an increased risk of cardiovascular diseases such as atherosclerosis, coronary artery disease, and stroke." (PMID 37375802, 2023). "A more detailed review of the de-identified EHRs of the two APOC3 19X carriers was performed to identify other possible cardiovascular disease risk factors." (PMID 30255797, 2018). "Increasing evidence has shown that loss-of-function mutations in APOC3 is associated with reduction in plasma triglycerides levels and will confer a benefit in patients at high risk for cardiovascular disease." (PMID 27624799, 2016). "Epidemiological studies and observational research have shown that increased levels of APOC3 lead to increased TG levels and a high risk of ASCVD, while LOF mutations in APOC3 are linked to decreased plasma TG levels and reduced cardiovascular disease risk among high-risk individuals." (PMID 38927431, 2024). "Several studies have suggested that targeting APOC3 could be a promising strategy for reducing the risk of cardiovascular disease." (PMID 37375802, 2023). "In addition, loss-of-function mutations in APOC3 have been associated with low circulating triglycerides and reduced incidence of cardiovascular disease." (PMID 35265678, 2022). "Indeed, genome-wide association studies have demonstrated that a null mutation in the APOC3 gene results in reduced expression of apolipoprotein C3, extremely low levels of triglycerides and reduced risk of cardiovascular disease." (PMID 35459248, 2022). "Higher values of CHOL, TG, hsCRP, and apoC3 are indicators of increased cardiovascular disease risk including, so we performed a regression analysis with a model of each of the four measurements as response, H, LS, and Std as quantitative variables and subject as a qualitative variable." (PMID 23990878, 2013). "Apolipoproteins have been demonstrated to play physiological roles on nutrition transport and energy metabolism, and numerous variants have been revealed in some apolipoproteins including ApoA1, ApoA5, ApoB, ApoC3 and ApoE, which are associated with the risk of cardiovascular disease." (PMID 21799896, 2011). "Besides, APOC3 was strongly related to cardiovascular disease risk." (PMID 35514958, 2022). "Given the critical role of APOC3 in triglyceride metabolism and its emerging connection to cardiovascular diseases, the discovery of these isoforms presents new opportunities for understanding APOC3 regulation and exploring potential therapeutic interventions." (PMID 40282372, 2025). "Although apolipoprotein C3 (APOC3) was discovered more than 50 years ago, it is now attracting a surge in interest as a potential new drug target for the prevention of cardiovascular disease (CVD)." (PMID 37972731, 2024). "Apolipoprotein C-III (ApoC3) is a key molecule of triglyceride metabolism that is known to be related to inflammation and cardiovascular disease." (PMID 35584319, 2022). "Considering our previous research and interest in the relationship between lipids and cardiovascular diseases, we herein used ELISA to validate three differentially abundant proteins involved in cholesterol metabolism: fetuin-B, APOC3, and CETP." (PMID 35265678, 2022). "Coincidentally, the APOC3 19X carrier with evidence of cardiovascular disease was also a carrier of IVS2 + 1G > A, representing to our knowledge potentially the first compound heterozygote for these mutations in the literature." (PMID 30255797, 2018).
cardiovascular disease (continued). "Similarly, apolipoprotein C3 (APOC3), a protein that is found in many lipoprotein particles and is associated with cardiovascular disease (CVD) enhances JAM-A expression in EC and increases monocyte adhesion to EC." (PMID 40728654, 2025). "ApoC3 plays a central role in the hydrolysis process of triglyceride (TG)-rich lipoproteins mediated by lipoprotein lipase (LPL), which levels are positively associated with the incidence of cardiovascular disease (CVD)." (PMID 35187136, 2022). "Thus, the addition of APOC3 R19X in a clinical setting may contribute to the patient’s risk assessment for cardiovascular disease, but it is not absolute and must be considered with other genetic and environmental risk factors." (PMID 30255797, 2018). "We also uncovered a rare splice acceptor variant in the apolipoprotein gene APOC3 (rs138326449, MAF = 0.2%) associated with RDW, a RBC trait that is considered a non-specific inflammatory marker and a predictor of cardiovascular diseases." (PMID 28787443, 2017). "Cardiovascular outcome trials are being considered for therapeutics that silence apolipoprotein C3 (APOC3) or angiopoietin-like 3 (ANGPTL3) because of their abilities to lower triglyceride-rich lipoproteins (TRLs) and their remnants in individuals with increased cardiovascular disease (CVD) risk." (PMID 40709279, 2025). "Based on previous reports, we also hypothesized that evidence of cardiovascular disease would be absent in EHRs of these APOC3 19X carriers with very low TG levels." (PMID 30255797, 2018).
cancer (30 papers, 1999 to 2025). A tumor composed of atypical neoplastic, often pleomorphic cells that invade other tissues. "We employed cis-Mendelian randomization and colocalization to evaluate the role of 5 lipid-perturbing drug targets (ANGPTL3, ANGPTL4, APOC3, CETP, and PCSK9) in risk of 5 cancers (breast, colorectal, head and neck, ovarian, and prostate)." (PMID 40511612, 2025). "An overexpression of APOC2 and APOC3 was reported by some studies reviewed in this manuscript and has been investigated in other cancers." (PMID 39194522, 2024). "On the contrary, all the cancer cell clusters had a strong connection with many of the macrophages in general (except APOC3+ and IGF2+ TAMs) when TAMs provided receptors instead, indicating possibly less specific crosstalk in this direction." (PMID 38169544, 2024). "We employed drug-target Mendelian randomization (MR) to systematically evaluate the effect of 5 approved or emerging lipid-perturbing drug targets for CVD (APOC3, ANGPTL3, ANGPTL4, CETP, and PCSK9) on risk of 5 cancers (breast, colorectal, head and neck, ovarian, and prostate)." (PMID 40511612, 2025). "Nonetheless, our findings suggesting little evidence of association of genetically proxied ANGPTL3, APOC3, CETP, and PCSK9 inhibition with cancer risk may help to deprioritize further evaluation of these proteins as intervention targets for cancer prevention." (PMID 40511612, 2025). "These suggest that these five cholesterol-related genes (APOA1, APOC3, ABCA1, NPC2, CD36) play an important role in cancer." (PMID 40302802, 2025). "APOC3, APOH, HPX, and FGB expression levels were highest in HCC and were greater in normal tissues than that in cancer tissues." (PMID 35449866, 2022). "The same trend was detected for apolipoprotein C-III (APOC3), while apolipoprotein E (APOE) and apolipoprotein A-II (APOA2) were more abundant in cancer coronas for L2 and less abundant for L1 and L3, respectively." (PMID 36142503, 2022). "The expression levels of APOC3, APOH, HPX, and FGB were the highest in HCC and were higher in normal tissues than in cancer tissues." (PMID 35449866, 2022). "The presence of all three novel APOC3 isoforms in both cancer cell lines and healthy liver tissue indicates that they are not a result of cancer-specific splicing alterations but rather part of the normal APOC3 transcript repertoire." (PMID 40282372, 2025).
metabolic disorders (19 papers, 2014 to 2026). "Understanding how APOC3 functions provides possibilities for treatments that aim to reduce levels and lessen the risks associated with heart and metabolic diseases." (PMID 39286687, 2024). "The lower rates of APOC3 −482TT and −455CC wild type alleles are identified as predominant factors underlying the apparent genetic resistance to metabolic diseases." (PMID 24972136, 2014). "APOC3 plays a role in more than just lipid processing; it is also linked to metabolic disorders." (PMID 39286687, 2024). "Variant alleles (−482T and −455C) of the APOC3 promoter region are associated with higher triglyceride levels, as such individuals with these alleles may be at higher risk of developing metabolic disorders." (PMID 24972136, 2014). "Understanding the relationship between APOC3 and the gut microbiota may offer new insights into the pathogenesis of metabolic disorders and potential therapeutic targets for modulating lipid metabolism and inflammation." (PMID 39479684, 2024).
infection (12 papers, 2014 to 2026). The state of being infected such as from the introduction of a foreign agent such as serum, vaccine, antigenic substance or organism. "We found that both γH2AX and APOC3 expression was restored during ΔcdtB infection when the strain expressed cdtB from a plasmid demonstrating a dependency on CdtB." (PMID 41326716, 2026). "Though we depleted the most abundant plasma proteins in infection challenge samples, our proteomics analysis identified relatively abundant proteins such as APOC3 and lysozyme." (PMID 41326716, 2026). "Further, the combination including four validated indexes and two classical infection indexes for septic diagnosis had the highest AUC‐ROC of 0.772, which was significantly better than that of ApoC3, VCAM1, and ApoE respectively, besides B2M." (PMID 34825737, 2022). "To test this possibility during infection, we examined APOC3 induction during infection with toxigenic Salmonella Javiana, a hazard group 2 non-typhoidal Salmonella serovar encoding typhoid toxin used for biosecurity reasons in place of the hazard group 3 pathogen S. Typhi." (PMID 41326716, 2026). "Furthermore, qPCR analysis revealed that H19 overexpression in hepatocytes led to the increased expression of numerous genes involved in lipid synthesis and storage, such as Gpam, Mogat, Fasn, Acaca, Apoc3, Srebp, Plin2, Plin3, Lipe and Mlxipl at 72 hours after Ad‐H19 infection." (PMID 31809000, 2020). "Specifically, the addition of FUC caused a further reduction in mRNA expression levels of NHE2, TRPV6, APOA1, APOA4, APOB, APOC3, and ASS1 compared to PEDV infection alone, while FUC supplementation counteracts PEDV-induced ARG1 upregulation." (PMID 40218394, 2025). "This was confirmed at the protein level, as infection decreased the amount of secreted AHSG and apolipoproteins APOA1, APOE and APOH, in both HepG2 and Huh7 conditioned media, as well as of APOB, APOC3 and SERPINF2 in Huh7." (PMID 34858876, 2021). "As seen in infection with HCVcc (JFH1), expression of ApoA1, ApoA2, ApoC1, ApoC2, ApoC3 and ApoE enhanced the formation of infectious particles of TH/JFH1 and S310/JFH1 chimeric viruses." (PMID 25502789, 2014).